CARD19 (caspase recruitment domain family member 19)
Description:
Plays a role in inhibiting the effects of BCL10-induced activation of NF-kappa-B. May inhibit the phosphorylation of BCL10 in a CARD-dependent manner.
Synonyms: BinCARD; C9orf89; MGC11115; bA370F5.1
Tractability: No criterion of Open Targets' tractability assessment is met for any kind of drug.
Gene: Protein-coding gene on chromosome 9 (93,096,161 to 93,113,283, forward strand). Ensembl gene ENSG00000165233.
Subcellular location: Nucleus (Isoform 1); Endoplasmic reticulum membrane (Isoform 2); Mitochondrion membrane
Subcellular location (Human Protein Atlas): Mitochondria
Gene Ontology:
Molecular function: CARD domain binding
Biological process: negative regulation of canonical NF-kappaB signal transduction
Cellular component: mitochondrion; cytosol; nucleus; endoplasmic reticulum membrane; mitochondrial membrane
Genetic constraint (gnomAD): Loss-of-function variants: 25 observed, 22.28 expected, observed/expected ratio (o/e) 1.12, 90% interval 0.82 to 1.57. The upper end of that interval is the gene's LOEUF score, 1.57, which puts it in group 6 of 6, group 1 being the genes least tolerant of losing a copy. Missense variants: 240 observed, 235.26 expected, observed/expected ratio (o/e) 1.02, 90% interval 0.92 to 1.13. Synonymous variants: 103 observed, 97.99 expected, observed/expected ratio (o/e) 1.05, 90% interval 0.89 to 1.24.
Homologues: Orthologues: macaque CARD19 (98% identical), chimpanzee CARD19 (92% identical), guinea pig CARD19 (90% identical), mouse Card19 (90% identical), pig CARD19 (87% identical), rat Card19 (86% identical), dog CARD19 (81% identical), rabbit CARD19 (69% identical).
Diseases named in the same sentence as CARD19 in open-access papers:
CARD19 is named in the same sentence as 11 diseases in open-access papers, as found by Europe PMC text mining. Sharing a sentence is not in itself a finding about the gene and the disease. The quoted sentences say what the papers report.
ischemic stroke (1 paper, 2025). A stroke disorder caused by obstruction of blood flow to the brain, due to thrombotic (local blood clot formation) or embolic (due to a blood clot or other material traveling from another site) event. "Remarkably, conditional knockdown of Card19 in microglia promoted poststroke neuroinflammation and worsened neurological outcomes in a mouse model of ischemic stroke." (PMID 40145957, 2025). "Here, we observed that CARD19 expression was significantly elevated in microglia in the penumbra after ischemic stroke via analyzing the spatial transcriptomic sequencing data of ischemic brain tissue, as well as in an in vitro model of microglial activation." (PMID 40145957, 2025). "However, the role of CARD19 in microglial biology and ischemic stroke remains unknown." (PMID 40145957, 2025).
Yersinia infection (1 paper, 2021). "Notably, Card19-deficient mice were more susceptible to Yersinia infection, indicating that cell lysis contributes to control of bacterial infections." (PMID 34648590, 2021).
bacterial infections (1 paper, 2021). "Our efforts to understand how cell death is regulated during bacterial infection led us to investigate the mitochondrial CARD-containing protein, CARD19, formerly known as BinCARD-2." (PMID 34648590, 2021).
tumor (1 paper, 2022). "The function of CARD19 remains mostly unknown, although one study has reported a contribution of CARD19 to IFNβ and IL-6 transcription in response to antiviral signaling in certain human tumor cell lines." (PMID 35406738, 2022).
CARD19 also shares sentences with these, for which no sentence is quoted: infection (2 papers); cancer (1); H1N1) virus infection (1); leukemia (1); pancreatic cancer (1); pancreatic ductal carcinoma (1); viral infection (1).